RPPH1 (ribonuclease P RNA component H1)
Diseases named in the same sentence as RPPH1 in open-access papers (continued):
Sharing a sentence is not in itself a finding about the gene and the disease.
tumor (18 papers, 2013 to 2025). "Related studies found that lncRNAs HLA-F-AS1, NBR2, PTTG3P, and RPPH1 induce the polarization response of tumor-associated Mφs by acting on the corresponding targets or pathways, thus participating in the pathological development of CRC." (PMID 35145526, 2022). "Therefore, we further explored the underling mechanism of the potential link between RPPH1 with tumor environment." (PMID 31685807, 2019). "In contrast, the ‘tumor cells 2’ cluster was characterized by genes associated with protein synthesis (Cmss1, Rpph1, Rps12, Lars2, Ncl2), tumorigenesis (Mt-Rnr2, Hmga2, Mab1b) and cell–cell communication (Gphn, Camk1d, Il31ra, Cmss1, Rpph1), which may be indicative of an inflammatory phenotype." (PMID 39769061, 2024). "Postoperative pathological analysis of clinical patients demonstrated greater tumor invasion in patients with high circ-RPPH1 expression compared to patients with low circ-RPPH1 expression." (PMID 40346652, 2025). "RPPH1 is an RNA subunit of RNase P, which is reported to be abnormally overexpressed in the neocortex of patients with seizures and in tumor tissues of patients with gastrointestinal cancer." (PMID 36619232, 2023). "The results showed that the RPPH1 expression was significantly impaired in tumor tissues compared to paired normal tissues." (PMID 36619232, 2023). "The results showed that the RPPH1 expression level was obviously increased in tumor tissues compared to the corresponding normal tissues." (PMID 36619232, 2023). "Further studies showed that RPPH1 is closely related to exosomes, which can transfer into Mφs by exosomes to mediate M2 polarization and promote tumor growth and migration." (PMID 35145526, 2022). "Previous studies demonstrated that long non‐coding regions of RPPH1 act as tumor promoters and play an important role in advancing tumorigenesis by targeting miR‐122." (PMID 33522650, 2021). "RPPH1 levels in plasma exosomes of CRC patients significantly decline after tumor removal, suggesting that RPPH1 downregulation inhibits the occurrence and development of CRC." (PMID 34485536, 2021). "Our in vivo xenograft mice experiments also demonstrated that down-regulation of RPPH1 significantly reduced THP-1 tumor growth." (PMID 31645843, 2019). "The effects of RPPH1 knockdown on in vivo tumor growth were evaluated in nude mice with xenografted THP-1 cells." (PMID 31645843, 2019). "Taken together, these results implied the pro-tumor functions of RPPH1 and anti-tumor functions of miR-330-5p in vivo." (PMID 31645843, 2019). "Further evaluation of the effect of RPPH1 in solid tumour formation in nude mice showed that lentivirus-mediated interference of shRPPH-1 lncRNA resulted to obvious changes in tumour size in vivo." (PMID 29200969, 2017). "The in vivo function of RPPH1 was illustrated by xenograft tumor models." (PMID 36619232, 2023). "Since miR-330-5p-specific inhibitor could reverse the retarded growth of AML cells with knockdown of RPPH1, miR-330-5p is more likely to function as a tumor suppressor." (PMID 31645843, 2019). "In addition, exosomal RPPH1 levels in blood plasma turned out to be higher in treatment-naive CRC patients but lower after tumor resection." (PMID 31685807, 2019). "Meanwhile, the RPPH1 level significantly decreased after tumor resection." (PMID 31685807, 2019). "RPPH1 knockdown significantly inhibited the growth of xenografted THP-1 tumor in nude mice." (PMID 31645843, 2019). "Moreover, we found that lentivirus-mediated interference of lncRNA RPPH1 inhibited tumour growth in nude mice." (PMID 29200969, 2017). "Besides, we measured the exosomal RPPH1 levels in 20 CRC patients 3 months after tumor resection." (PMID 31685807, 2019). "In summary, our findings show that serum EV lncRNA RMRP, RPPH1 and linc-ROR are abnormally expressed in GC and are significantly correlated with tumor size, stage, metastasis, and other clinicopathological factors." (PMID 39925803, 2025).
tumor (continued). "The results showed that lncRNA RMRP, RPPH1, and linc-ROR were significantly correlated with tumor diameter, lymphatic metastasis, distal metastasis, and TNM stage (all P < 0.05)." (PMID 39925803, 2025). "Through shRNA (short hairpin RNA)-mediated knockdown of RPPH1 expression in AML cells, we revealed the critical roles of RPPH1 in promoting the malignant behaviors of AML cells both in vitro and in AML tumor xenograft mice model." (PMID 31645843, 2019). "Testing of the RNA expression levels of the four upregulated genes in the tumour xenografts showed that decreased expression of the ADAM10 and IGF1R genes in the RPPH1 knockdown group." (PMID 29200969, 2017). "We demonstrated that miR-122 expression was decreased in tumor tissues and HCC cells compared to normal controls, and the decrease, which was correlated with poor overall survival, had a significant linear correlation with the increase in RPPH1 in HCC." (PMID 36619232, 2023). "Similarly, lncRNA RPPH1 was significantly overexpressed in CRC tissues, and the RPPH1 upregulation was related to a poor prognosis and an advanced tumor/node/metastasis (TNM) stage." (PMID 38067805, 2023). "RPPH1 promotes CRC cells metastasis by binding to TUBB3, thus inhibiting its ubiquitination and enhancing exosomes-mediated macrophages M2 polarization and influences the tumor microenvironment." (PMID 31685807, 2019). "It is worth noting that miR-330-5p inhibition can not fully reverse the anti-tumor effects of RPPH1 knockdown in AML cells." (PMID 31645843, 2019).
cancer (9 papers, 2017 to 2023). A tumor composed of atypical neoplastic, often pleomorphic cells that invade other tissues. "The cancer cells release exosomes containing LncRNA RPPH1 transported into macrophages causes induced polarization of M2 phenotype." (PMID 34303380, 2021). "Like RPPH1, RMRP ncRNA is similarly overexpressed and associated with unfavorable prognoses across a multitude of cancer contexts, and evidence suggests RMRP also contributes to proliferation through novel protein interactions and miRNA sequestration." (PMID 36754845, 2023). "The expression of the lncRNA RPPH1 gene was significantly increased in cancer sites when compared with adjacent sites, as demonstrated by qPCR, and in the breast tissue chip, as demonstrated by ISH." (PMID 29200969, 2017). "RP11-361F15.2 and RPPH1 are predicted to sponge miRNA (in cancer cells) to promote cancer invasion." (PMID 37190145, 2023). "Since the epithelial-to-mesenchymal transition (EMT) is a crucial factor promoting the migration and invasion of cancer cells, we further investigated whether RPPH1 regulates the EMT of HCC cells." (PMID 36619232, 2023). "Here we explore the biogenesis, functions, and cancer connections for both RPPH1 and RMRP." (PMID 36754845, 2023). "Moreover, the expression of lncRNA RPPH1 in the cytoplasm and nucleus of cancer tissue cells was higher than that in normal tissues." (PMID 29200969, 2017). "Independently of RNase P, RPPH1 ncRNA interacts with additional proteins as well as specific miRNAs to functionally promote cell growth and proliferation, and growing evidence suggests that these mechanisms drive tumorigenesis and metastasis in a variety of cancers." (PMID 36754845, 2023). "Therefore, we hypothesized that exosomal RPPH1 strongly involved in the communication between cancer cells and TAMs." (PMID 31685807, 2019). "Taken together, RPPH1 appears likely to play an important role in coupling Pol III transcription to cell growth mechanisms and holds future promise as a potential biomarker and target in cancer contexts." (PMID 36754845, 2023). "For instance, the LncRNA RPPH1 and UCA1 increase facilitates the metastasis in CRC by increasing M2 conversion needs further work in other cancer to use as a potential therapeutic target might sustain the activation of M1 macrophages." (PMID 34303380, 2021).
infection (1 paper, 2025). The state of being infected such as from the introduction of a foreign agent such as serum, vaccine, antigenic substance or organism. "In contrast, the lincRNAs POLG-DT and the ribonuclease P RNA component H1 (RPPH1) showed different expression levels at different days of infection (i.e., at 1hPI, 1dPI, and 3dPI) compared to uninfected cells." (PMID 40510596, 2025). "Similar to POLG-DT, RPPH1 also exhibited an oscillating expression pattern post infection, but reversed to that of POLG-DT, i.e., expression levels of RPPH1 in Delta-infected NHBE cells were upregulated at 1dPI but were decreased at 1hPI and 3dPI." (PMID 40510596, 2025).
neurodegenerative disease (1 paper, 2019). A disorder of the central nervous system characterized by gradual and progressive loss of neural tissue and neurologic function. "Multiple studies have revealed that the long non-coding RNA RPPH1 (Ribonuclease P RNA Component H1) is involved in disease progression of solid tumors and neurodegenerative diseases." (PMID 31645843, 2019).
RPPH1 also shares sentences with these, for which no sentence is quoted: esophageal cancer (2 papers); cervical cancer (1); IgA nephropathy (1); lentivirus infection (1); leukemia (1); non-small cell lung carcinoma (1); Seizure (1).